USP13 (ubiquitin specific peptidase 13)
Description:
Deubiquitinase that mediates deubiquitination of target proteins such as BECN1, MITF, SKP2 and USP10 and is involved in various processes such as autophagy, endoplasmic reticulum-associated degradation (ERAD), cell cycle progression or DNA damage response. Alternatively, forms with NEDD4 a deubiquitination complex, which subsequently stabilizes VPS34 to promote autophagy. Recruited by nuclear UFD1 and mediates deubiquitination of SKP2, thereby regulating endoplasmic reticulum-associated degradation (ERAD). Also regulates ERAD through the deubiquitination of UBL4A a component of the BAG6/BAT3 complex. Mediates stabilization of SIAH2 independently of deubiquitinase activity: binds ubiquitinated SIAH2 and acts by impairing SIAH2 autoubiquitination. Regulates the cell cycle progression by stabilizing cell cycle proteins such as SKP2 and AURKB. In addition, plays an important role in maintaining genomic stability and in DNA replication checkpoint activation via regulation of RAP80 and TOPBP1. Deubiquitinates the multifunctional protein HMGB1 and subsequently drives its nucleocytoplasmic localization and its secretion. Positively regulates type I and type II interferon signalings by deubiquitinating STAT1 but negatively regulates antiviral response by deubiquitinating STING1.
Synonyms: ISOT-3; ISOT3
Tractability: PROTAC: UniProt records ubiquitination sites on it; ubiquitination databases record sites on it; a small molecule that binds it is known.
Target class: Cysteine protease; Cysteine protease CA clan; Protease; Enzyme; Cysteine protease C19 family
Gene: Protein-coding gene on chromosome 3 (179,653,004 to 179,804,366, forward strand). Ensembl gene ENSG00000058056.
Subcellular location: Cytoplasm
Subcellular location (Human Protein Atlas): Cytosol; Nucleoplasm
Pathways (Reactome):
Metabolism of proteins: Ub-specific processing proteases
Signal Transduction: Regulation of PTEN stability and activity
Gene Ontology:
Molecular function: BAT3 complex binding; cysteine-type deubiquitinase activity; cysteine-type endopeptidase activity; K48-linked deubiquitinase activity; proteasome binding; protein binding; protein-folding chaperone binding; ubiquitin binding; ubiquitin protein ligase binding; ubiquitin-like protein ligase binding; zinc ion binding
Biological process: cell population proliferation; positive regulation of ERAD pathway; protein K29-linked deubiquitination; protein K6-linked deubiquitination; protein K63-linked deubiquitination; protein stabilization; regulation of autophagy; regulation of DNA-templated transcription; melanocyte differentiation; protein deubiquitination; positive regulation of proteasomal protein catabolic process
Cellular component: cytoplasm; cytosol; nucleoplasm
Genetic constraint (gnomAD): Loss-of-function variants: 67 observed, 106.99 expected, observed/expected ratio (o/e) 0.63, 90% interval 0.51 to 0.77. The upper end of that interval is the gene's LOEUF score, 0.77, which puts it in group 3 of 6, group 1 being the genes least tolerant of losing a copy. Missense variants: 919 observed, 1,092.9 expected, observed/expected ratio (o/e) 0.84, 90% interval 0.8 to 0.89. Synonymous variants: 364 observed, 387.68 expected, observed/expected ratio (o/e) 0.94, 90% interval 0.86 to 1.02.
Homologues: Orthologues: chimpanzee USP13 (99% identical), macaque USP13 (99% identical), dog USP13 (98% identical), pig USP13 (98% identical), rabbit USP13 (96% identical), mouse Usp13 (96% identical), rat Usp13 (93% identical), guinea pig USP13 (93% identical), tropical clawed frog usp13 (77% identical), zebrafish usp13 (75% identical). Paralogues in human: USP5 (60% identical), USP24 (16% identical), USP15 (14% identical), USP4 (14% identical), USP9X (14% identical), USP32 (14% identical), USP11 (13% identical), USP19 (13% identical), USP38 (13% identical), USP6 (13% identical), USP8 (13% identical), USP37 (13% identical), and 59 more.
Diseases named in the same sentence as USP13 in open-access papers:
USP13 is named in the same sentence as 96 diseases in open-access papers, as found by Europe PMC text mining. Sharing a sentence is not in itself a finding about the gene and the disease. The quoted sentences say what the papers report.
ovarian carcinoma (22 papers, 2016 to 2025). A malignant neoplasm originating from the surface ovarian epithelium. "We previously demonstrated that USP13-amplified ovarian cancer cells rely on the USP13-associated deubiquitination pathway for their proliferation and survival." (PMID 36612196, 2022). "Notably, mutation of Thr122 diminished the effect of USP13 on the increased proliferation of ovarian cancer cells." (PMID 36612196, 2022). "Ubiquitin specific peptidase 13 (USP13) is a key regulatory factor driving ovarian cancer metabolism, and silencing USP13 significantly inhibits cell proliferation." (PMID 40746599, 2025). "As a deubiquitinating enzyme, USP13 exhibits both tumor-promoting and tumor-suppressing effects and is related to the initiation, progression, and apoptosis of breast, bladder, and ovarian cancers and other tumors." (PMID 40746889, 2025). "USP13 also facilitates glioblastoma and ovarian cancer occurrence through stabilizing c-MYC and ACLY/OGDH." (PMID 40746889, 2025). "USP13 functions as an oncogenic factor during tumorigenesis in ovarian cancer by regulating cancer metabolism and metastasis." (PMID 38093367, 2023). "Previously, knockdown of USP13 sensitized USP13-overexpressing human ovarian cancer cells to the treatment of AKT inhibitor." (PMID 35173307, 2022). "Ubiquitin-Specific Peptidase 13 (USP13) gene copy is strongly amplified in human epithelial ovarian cancer, and high USP13 expression is correlated with poor survival outcomes." (PMID 35173307, 2022). "Ubiquitin-specific Peptidase 13 (USP13) is highly amplified and promotes tumorigenesis and metastasis in ovarian cancer." (PMID 36612196, 2022). "High expression of USP13 protein is positively correlated with poor survival outcomes in ovarian cancer patients." (PMID 36612196, 2022). "Phosphorylation of USP13 at Thr122 by CK2 increases the stability of USP13, which in turn promotes ovarian cancer proliferation." (PMID 36612196, 2022). "To study the function of phosphorylation on Thr122 of USP13 in ovarian cancer, we generated an anti-phospho-Thr122 USP13 antibody (anti-pT122 antibody)." (PMID 36612196, 2022). "Here, we report that USP13 is a CK2 substrate and that this phosphorylation stabilizes USP13 protein both in vitro and in ovarian cancer cells." (PMID 36612196, 2022). "The mutation of the Thr122 phosphorylation site of USP13 reduced the proliferation of ovarian cancer cells compared with USP13 wild-type, suggesting that Thr122 phosphorylation is important for the oncogenic function of USP13 in ovarian cancer." (PMID 36612196, 2022). "Although the diverse roles of USP13 have been studied in various cancer types, including ovarian cancer, the regulatory mechanism of PTMs on USP13 is little known." (PMID 36612196, 2022). "To investigate the in vivo role of USP13 in ovarian cancer, we generated USP13 conditional overexpressing ovarian cancer GEMMs." (PMID 35173307, 2022). "To identify phosphorylation sites on USP13 in ovarian cancer, we performed immunoprecipitation (IP) of endogenous USP13 in human ovarian cancer HeyA8 cells." (PMID 36612196, 2022). "In ovarian cancer, USP13 was shown to promote glutamine-dependent reductive carboxylation for lipogenesis." (PMID 35307036, 2022). "Our data demonstrated that CK2-mediated phosphorylation at Thr122 regulates the half-life of the USP13 protein in ovarian cancer cells." (PMID 36612196, 2022). "We also reveal that phosphorylation at Threonine 122 of USP13 promotes the proliferation of ovarian cancer cells." (PMID 36612196, 2022). "Next, we examined the phosphorylated Thr122 (pT122) on endogenous USP13 in immortalized human fallopian tube secretory epithelial cells and various human ovarian cancer cell lines with the validated anti-pT122 antibody." (PMID 36612196, 2022).
ovarian carcinoma (continued). "The abundance of the phosphorylated form (pT122) of USP13 was correlated to the total level of USP13 in most ovarian cancer cells." (PMID 36612196, 2022). "We overexpressed FLAG-tagged wild-type USP13 (WT) and phospho-mutant USP13 (T122A) in two human ovarian cancer cell lines." (PMID 36612196, 2022). "The GEMMs, primary ovarian cancer cells, and a syngeneic study demonstrated that USP13 enhances tumorigenic and metastatic phenotypes of ovarian cancer." (PMID 35173307, 2022). "USP13 gene is amplified in serious ovarian cancers and specifically deubiquitinates and thus upregulates two key metabolic key enzymes, ATP citrate lyase (ACLY) and oxoglutarate dehydrogenase (OGDH)." (PMID 35898882, 2022). "In lung and ovarian cancer cells, USP13 deubiquitinates and stabilizes MCL1, a key member of the anti-apoptotic BCL-2 family." (PMID 35898882, 2022). "CHX chase assay revealed that the phosphorylated USP13 at Thr122 was more stable than the total USP13 in ovarian cancer cells." (PMID 36612196, 2022). "To understand the biological role of Thr122 phosphorylation of USP13 in ovarian cancer, we examined the effect of inhibiting T122 phosphorylation on cell proliferation." (PMID 36612196, 2022). "USP13 is highly amplified in human ovarian cancer, and elevated expression of USP13 promotes tumorigenesis and metastasis of ovarian cancer." (PMID 36612196, 2022). "Future studies will focus on proteomics, metabolomics, and molecular mechanistic understanding of how USP13 promotes tumorigenesis and metastatic features of ovarian cancer." (PMID 35173307, 2022). "USP13 gene copy is frequently amplified in several human cancers, such as lung, esophagus, and ovarian cancer." (PMID 36612196, 2022). "Phosphorylated Thr122 (pT122) on endogenous USP13 was observed in most human ovarian cancer cells, and the abundance of this phosphorylation was correlated to the total level of USP13." (PMID 36612196, 2022). "USP13 also increased the tumorigenic and metastatic abilities of primary murine ovarian cancer cells in a syngeneic mouse study." (PMID 35173307, 2022). "In human ovarian cancers, USP13 was frequently amplified and showed to be critical for glutamine catobolism, and its depletion represses mitochondrial function." (PMID 35307036, 2022). "Collectively, USP13 is highly amplified in HGSOC, and it is associated with poor survival for ovarian cancer patients." (PMID 35173307, 2022). "This experiment showed that CK2 was co-immunoprecipitated with USP13, indicating that USP13 interacts with CK2 in ovarian cancer cells." (PMID 36612196, 2022). "Our previous study demonstrated that the depletion of USP13 selectively killed the USP13-highly expressing ovarian cancer cells and suppressed ovarian tumor growth in vivo, suggesting an oncogenic addictive phenotype of USP13-amplified ovarian cancer cells." (PMID 36612196, 2022). "USP13 is abnormally highly expressed in ovarian cancer and participates in lipid synthesis and tumorigenesis through deubiquitination of ACLY39." (PMID 35449157, 2022). "A previous study reports that USP13 knockdown suppresses ovarian cancer cell proliferation in vitro and tumor formation in vivo." (PMID 33195243, 2020). "For example, USP13 is overexpressed in ovarian cancer, and its overexpression significantly predicts poor clinical outcomes." (PMID 33195243, 2020). "Studies have reported that ubiquitin-specific peptidase 13 (USP13) was the main regulator of ovarian cancer metabolism." (PMID 33194756, 2020). "Han el al reported that USP13 gene is amplified in serious ovarian cancers and its overexpression is correlated with poor clinical outcome, indicating a potential therapeutic role of USP13 in ovarian cancer." (PMID 31200745, 2019). "Our study has provided a rational basis for designing clinical trials of USP13 inhibitors in the future to control solid tumors including lung and ovarian cancer." (PMID 29335437, 2018).
ovarian carcinoma (continued). "Here, we provided several lines of evidence to support that MCL1 was a deubiquitination target of USP13 in lung and ovarian cancer." (PMID 29335437, 2018). "28% ovarian cancers show amplification of USP13, which is higher than other BRCA1-A complex members." (PMID 28569838, 2017). "In our study, both the Oncomine data set and the TCGA data set show the amplification of USP13 gene in ovarian cancer." (PMID 28569838, 2017). "Depleting or inhibiting USP13 sensitizes ovarian cancer cells to cisplatin and PARP inhibitor (olaparib) while overexpression of USP13 renders ovarian cancer cells resistant to chemotherapy." (PMID 28569838, 2017). "Here, the authors show that USP13 is amplified in ovarian cancer and its protein product, a deubiquitinase, drives tumour progression by rewiring the metabolism of cancer cells by stabilising two critical metabolic enzymes." (PMID 27892457, 2016). "Here we identify ubiquitin-specific peptidase 13 (USP13) as a master regulator that drives ovarian cancer metabolism." (PMID 27892457, 2016). "In conclusion, we identified CK2-mediated phosphorylation of USP13 in ovarian cancer." (PMID 36612196, 2022). "Inhibition of USP13 sensitized primary ovarian cancer cells to the effects of an AKT inhibitor." (PMID 35173307, 2022). "Although the biochemical and molecular functions of USP13 have been explored in the various contexts of human cancer cells, including ovarian cancer, the in vivo pathological function of USP13 in cancer development and progression remains unknown." (PMID 35173307, 2022). "Here, we found that USP13 is phosphorylated at Thr122 in ovarian cancer cells." (PMID 36612196, 2022). "Our study proposes that targeting phosphorylation could inhibit the oncogenic function of USP13 in ovarian cancer." (PMID 36612196, 2022). "Inhibition of the phosphorylation of USP13 downregulated USP13 protein stability and reduced the proliferation of ovarian cancer cells, which may lead to novel therapeutics targeting USP13 in USP13-amplified cancers." (PMID 36612196, 2022). "Our data suggest that inhibiting Thr122 phosphorylation of USP13 may provide an effective therapeutic strategy for targeting USP13 in USP13-amplified ovarian cancer." (PMID 36612196, 2022). "However, there is little known about USP13 post-translational modifications and their role in ovarian cancer." (PMID 36612196, 2022). "Additionally, USP13 is reported to improve the DNA damage response by recruiting the RAP80-BRCA complex to DNA damage sites in ovarian cancer, indicating that USP13 is a potential target to enhance the effectiveness of DDR inhibitors in cancers." (PMID 36564767, 2022). "USP13 amplification in human HGSOC may contribute to the development of resistance of PI3K/AKT inhibitors in ovarian cancer, and targeting USP13 may overcome cancer cell resistance against targeted therapy for PI3K/AKT/mTOR pathway." (PMID 35173307, 2022). "In our previous study, we identified that USP13 increased both energy production and biosynthesis in human ovarian cancer cells by stabilizing Oxoglutarate Dehydrogenase (OGDH) and ATP Citrate Lyase (ACLY), which are key metabolic enzymes driving the reprogramming of ovarian cancer cell metabolism." (PMID 35173307, 2022). "Our findings may reveal a novel regulatory mechanism for USP13, which may lead to novel therapeutic targeting of USP13 in ovarian cancer." (PMID 36612196, 2022). "Interestingly, USP13 was recently shown to deubiquitinate and stabilise the pro-survival protein Mcl-1 in lung and ovarian cancers." (PMID 33627786, 2021). "Like cervical cancer, ovarian cancers are squamous cell carcinomas; therefore, we hypothesised that USP13 might also regulate Mcl-1 in cervical cancer cells." (PMID 33627786, 2021). "Overall, USP13 functions as an essential regulator of DNA repair, and plays a vital role in the resistance of ovarian cancer cells to chemotherapy, and may provide a new approach for the treatment of ovarian cancer." (PMID 34177595, 2021).